NLRP3 (NLR family pyrin domain containing 3)
Diseases named in the same sentence as NLRP3 in open-access papers (continued):
Sharing a sentence is not in itself a finding about the gene and the disease.
gout (continued). "Monosodium urate (MSU) crystal can stimulate the activation of NLRP3 inflammasome and the secretion of inflammatory cytokines such as IL‐1β, which can induce the progress of gout." (PMID 32656909, 2020). "In vitro and in vivo studies have reported the activation and upregulation of NLRP3 in painful conditions including gout and rheumatoid arthritis, while inhibition of NLRP3 function or expression can mediate analgesia." (PMID 32973552, 2020). "Monosodium urate (MSU) crystals induce the autoinflammatory disease gout and activate the NLRP3 inflammasome." (PMID 32187211, 2020). "Innate immune pathways are essential in the pathogenesis of gout, particularly the activation of NLRP3 inflammasome, which leads to the release of IL-1β and other pro-inflammatory cytokines." (PMID 33568990, 2020). "There is accumulating evidence for NLRP3 and cytokine expression in gout pathology as well, which is evidenced by studies conducted in animal models and human clinical studies." (PMID 32973552, 2020). "OLT1177 was reported to potently inhibit inflammatory cytokine processing by NLRP3 in models of gout and osteoarthritis." (PMID 33036374, 2020). "Our study first identified the role of P2Y14R/cAMP/NLRP3 signaling pathway in acute gouty arthritis, which provides a novel insight into the pathological mechanisms of pyroptosis-related diseases." (PMID 32457291, 2020). "As we observed the important role of HSP60 in the TLR4 signaling pathway and NLRP3 inflammasome activity, this prompted us to investigate its role in gout." (PMID 33488933, 2020). "Our study is the first research to reveal the role of BRD4 in MSU-induced NLRP3 inflammasome activation in acute gouty arthritis." (PMID 33162822, 2020). "Our results suggested that gallic acid enhances the Nrf2 signaling to suppress NLRP3 inflammasome activation and pyroptosis and alleviate NLRP3-dependent gouty arthritis." (PMID 33365024, 2020). "Then, the pathogen‐associated molecular patterns (PAMP) or damage‐associated molecular patterns (DAMP), such as extracellular adenosine triphosphate (ATP), nigericin and monosodium urate (MSU) crystals (gout aetiology), can activate the NLRP3 inflammasome." (PMID 32656909, 2020). "These uric acid crystals activate the NACHT, LRR and PYD domains-containing protein 3 (NLRP3) inflammasome, which is involved in chronic inflammatory diseases, including gouty arthritis." (PMID 31979265, 2020). "MSU-triggered NLRP3 activation and derived cascades of innate immune responses have been expansively confirmed in gout etiology." (PMID 33505406, 2020). "In this study, we investigated the influence of gallic acid on NLRP3 inflammasome activation and pyroptosis in macrophages, and its effect on gouty arthritis mice." (PMID 33365024, 2020). "Oridonin has been reported to be an effective anti‐inflammatory molecule in the treatment of gouty arthritis, type 2 diabetes, and peritonitis and it functions by inhibiting NLRP3 activation." (PMID 32219880, 2020). "This molecule demonstrated therapeutic efficacy in mouse models of NLRP3‐driven gouty arthritis and CAPS." (PMID 32770571, 2020). "In conclusion, our in vivo model in mice uncovers an unsuspected complexity of the pathogenesis of gout triggered by urate crystals, as illustrated by its independence from the NLRP3 inflammasome." (PMID 32104502, 2020). "Canakinumab is an IL-1β-neutralizing antibody approved for the treatment for CAPS-associated symptoms which also reduced the incidence of two other NLRP3-related diseases, arthritis and gout." (PMID 32849554, 2020). "The in vivo experiments also suggested that gallic acid can alleviate MSU-induced gouty arthritis by suppressing NLRP3 inflammasome activation." (PMID 33365024, 2020). "Since NLRP3 plays a significant role in innate immunity, dysregulated activation results in inflammatory conditions such as atherosclerosis, Type-II diabetes, gout and various neurodegenerative disorders." (PMID 33424855, 2020).
gout (continued). "Owing to the effect of colchicine on suppressing MSU-induced NLRP3 inflammasome activation, thus dampening IL-1β release and neutrophil recruitment, it has long been used in clinic for the treatment of gout." (PMID 30761140, 2019). "OxLDL and other types of crystals, including uric acid crystals as seen in gout, are also known to activate the pro-inflammatory NLRP3 response." (PMID 31357404, 2019). "In support of this view, several studies have shown that MSU crystals activated NLRP3 assembly in PBMCs from gout patients." (PMID 31200447, 2019). "Of interest, the implementation of gouty arthritis animal models has allowed to better clarify the pathophysiological role of NLRP3 in gout." (PMID 31200447, 2019). "Mitochondrial damage is closely related to the activation of NLRP3 inflammasome and the inflammatory response of gout, especially mitochondrial reactive oxygen species (ROS) which affect the assembly of NLRP3 inflammasome." (PMID 31455356, 2019). "In conclusion, EGCG inhibits acute gout inflammation, including proinflammatory cytokine release and neutrophil infiltration into the lesion site, mediated by the suppression of NLRP3 inflammasome activation in macrophages." (PMID 31174271, 2019). "Several lines of evidence have shown that various NLRP3-targeting natural compounds can exert anti-inflammatory effects on MSU-induced gouty arthritis." (PMID 31200447, 2019). "Further, the chicory extract significantly decreased IL-1β release by suppressing the NF-κB and NLRP3 signaling pathways in gout rats." (PMID 31590257, 2019). "QZTB suppressed the serum IL-1β (P < 0.01) and TNF-α (P < 0.001) levels in the MSU crystal-induced rats, suggesting that QZTB can inhibit NLRP3 pathways contributing to arthritis in this acute gout model." (PMID 31885675, 2019). "The inhibitory effects of EGCG on the NLRP3 inflammasome make EGCG a promising therapeutic option for NLRP3-dependent diseases such as gout." (PMID 31174271, 2019). "We further investigated the mechanisms of the anti-inflammatory effect of chicory on gout from the NLRP3 signaling pathway." (PMID 31590257, 2019). "MSU crystals engage the Nlrp3 inflammasome, leading to the activation of caspase-1 and production of IL-1β and IL-18 within gout-affected joints, promoting the influx of neutrophils and monocytes." (PMID 31803174, 2019). "The nucleotide-binding oligomerization domain (NOD)-like receptor (NLR) family pyrin domain containing 3 (NLRP3) inflammasome is responsible for the gout inflammatory symptoms induced by MSU crystals." (PMID 31174271, 2019). "The protein expression levels of inflammasome components (ASC, caspase-1, and NLRP3) in ankle synovial tissues of MSU-induced gout rats were measured by immunohistochemistry." (PMID 31590257, 2019). "MSU deposition is the primary cause of gouty arthritis and delivery of MSU into the joints can result in NLRP3 inflammasome-dependent arthritis in mice." (PMID 29959312, 2018). "The small and orally active molecule OLT1777 inhibits the formation of the NLRP3 inflammasome and reduces the severity of reactive and gouty arthritis." (PMID 30075804, 2018). "Activation of the NLRP3 inflammasome in gout amplifies the inflammatory response and mediates further damage." (PMID 30075804, 2018). "Our data provide a direct mechanism for this observation, particularly given that gout is an NLRP3-dependent pathology." (PMID 29884801, 2018). "It was suggested that the P2X7R/NLRP3/IL-1β pathway is involved in many inflammatory diseases including gout." (PMID 30123371, 2018). "The favorable phase I safety profile of OLT1177 combined with the reported inhibitory effects on NLRP3 inflammasome and IL-1β release led to approval of the molecule for phase II development in gout." (PMID 30075804, 2018). "Activation of the NLRP3 inflammasome and subsequent production of interleukin-1β is a key inflammatory process in gout." (PMID 30376864, 2018).
gout (continued). "The NLRP3 inflammasome is also relevant in metabolic diseases, such as gouty arthritis and type 2 diabetes mellitus." (PMID 29686531, 2018). "Recent studies have revealed involvement of the NLRP3 inflammasome in various human diseases, such as multiple sclerosis (MS), gout, type 2 diabetes, and inflammatory bowel diseases." (PMID 29850543, 2018). "The mechanism causing acute inflammation in gout patients initiates from MSU crystal deposition, and then MSU interacts with macrophages to activate NLRP3 inflammasome and IL-1β release." (PMID 29453348, 2018). "The essential role of the NLRP3 inflammasome in acute gout attacks was recognized less than a decade ago, and the mechanisms through which MSU crystals activate the NLRP3 inflammasome are still under study." (PMID 28357052, 2017). "In this study, we report a biological mechanism that can suppress inflammation and ameliorate gout pain via NLRP3 inflammasome suppression in macrophages." (PMID 28376889, 2017). "Certain first signal NLRP3 inflammasome activators can promote and sustain chronic low-grade inflammation, clinically evident chronic synovitis in gout, and acute inflammatory flares in response to deposited urate crystals." (PMID 28818081, 2017). "Suppression of the NLRP3 inflammasome in macrophages contributes to the amelioration of gout pain by procyanidins." (PMID 28376889, 2017). "Our study aimed to find a food-derived compound to attenuate gout pain via the specific inhibition of the NLRP3 inflammasome in macrophages." (PMID 28376889, 2017). "As an indicator of acute gouty arthritis, phagocytosis of MSU by macrophages can activate the NLRP3 inflammasome, which is considered to play a critical role in gouty arthritis." (PMID 26890073, 2016). "The NLRP3 inflammasome has been shown to participate in development of cancer, as well as various inflammation-related diseases, including gout, diabetes and Alzheimer’s disease." (PMID 27796369, 2016). "Gouty arthritis is caused by the deposition of uric acid crystals, which induce the activation of NOD-like receptor family, pyrin domain containing 3(NLRP3) inflammasome." (PMID 27934918, 2016). "Current studies show that NLRP3 inflammasome signaling pathways is involved in the pathogenesis of gout and pseudogout." (PMID 27034595, 2016). "Together, oral administration of CAPE effectively attenuated the inflammatory symptoms of gouty arthritis by suppressing NLRP3 inflammasome activation." (PMID 27934918, 2016). "The discovery of the inflammasome propelled forward the understanding of the pathogenesis of gout, with the importance of the NLRP3 inflammasome now well established." (PMID 25975607, 2015). "For gout the role of the NLRP3 inflammasome has been clearly defined and it will be of great interest to follow the development of NLRP3 inhibitors such as CRID3 that have the capability to be of significant clinical benefit during disease flares." (PMID 25975607, 2015). "A pivotal role of the inflammasome has been suggested also in gout, where monosodium urate crystals activate NLRP3." (PMID 26523150, 2015). "Phagocytosis of MSU by macrophages can activate the NLRP3 inflammasome, which is considered to play a critical role in gouty arthritis." (PMID 26399911, 2015). "Accumulation of monosodium urate is characteristic of gout in humans, but only recently aberrant NLRP3 inflammasome activation, NLRP3-dependent caspase-1 activation, and release of IL-1β have been linked to its pathology." (PMID 25324778, 2014). "Additionally, endogenous DAMPs such as extracellular ATP, gout associated uric acid crystals, fibrillar amyloid beta or cholesterol crystals, and also environmental products like silica crystals, asbestos fibers and nanomaterials have been shown to give rise to NLRP3 inflammasome activation." (PMID 23666718, 2013).
gout (continued). "The potential pivotal role of the components of innate immunity, especially TLR2/TLR4 and the NLRP3 inflammasome, in this disease, seems attractive as potential target candidates for the treatment of gout." (PMID 23738004, 2013). "MSU microcrystals, found locally encrusted in the bone matrix of chronic gout, activate phagocytosis and NLRP3-dependent autophagy in OBs, but remain intact in permanent autophagosomes while deregulating OB functions." (PMID 24456929, 2013). "MSU and CPPD crystals, inflammatory drivers of gout, and pseudogout respectively also activate the NLRP3-inflammasome." (PMID 23024646, 2012). "Recent studies suggested that MSU-mediated NLRP3 inflammasome activation and subsequent IL-1β production in macrophages as key events in initiation of gout." (PMID 22608202, 2012). "Particulate matter such as gout and pseudogout-associated uric acid crystals, monosodium urate and calcium pyrophosphate dihydrate and fungal infection activate the NLRP3/NALP3 inflammasome in a P2X7-independent manner." (PMID 22315529, 2010). "NLRP3-containing inflammasomes are linked to contact hypersensitivity, sunburn, essential hypertension, gout and pseudogout, Alzheimer's disease, and elevated expression of NLRP3 is detected in synovial fluids of RA patients." (PMID 20482797, 2010). "The classical example is gout, driven by NLRP3 inflammasome activation." (PMID 41550415, 2026). "Once activated, the NLRP3 inflammasome stimulates the secretion of pro-inflammatory cytokines such as IL-1β, which is a key mediator of the characteristic inflammatory cascade in gout." (PMID 40370447, 2025). "Studies have found that the level of SHP decreases in gout mice, negatively regulating the activation of NLRP3 inflammasome, which may affect the migration of leukocytes and inflammatory response during leukocyte activation." (PMID 40606658, 2025). "Our study hypothesizes that this dual-targeted approach will provide superior disease control by addressing hyperuricemia and NLRP3-mediated inflammation, thereby reducing gout severity, preventing recurrent flares, and preserving joint integrity." (PMID 40430581, 2025). "Moreover, monosodium urate crystals that accumulate in gout induce the formation of the NLRP3 inflammasome, which is activated early in vascular inflammation." (PMID 40266325, 2025). "Whole-genome sequencing studies further identify novel genetic loci (RCOR1, FSTL5-MIR4454) and transporter variants (ABCG2, SLC22A12) associated with early-onset gout, with RCOR1 promoting NLRP3 inflammasome activation and IL-1β release, which are key drivers of gouty inflammation." (PMID 40880930, 2025). "Activation of NLRP3 inflammasomes plays a critical role in gout pathogenesis." (PMID 41377556, 2025). "Studies have found that hyperuricemia exacerbates periodontitis and gouty arthritis by activating NLRP3, suggesting a close link between metabolic abnormalities and inflammation, and indicating that NLRP3 inhibitors could be therapeutic for such conditions." (PMID 41415576, 2025). "Prospective pharmacovigilance studies should evaluate whether concomitant administration of NLRP3 inhibitors (e.g., colchicine) or IL-1β-neutralizing biologics could mitigate FGF21-associated gout flare risk in predisposed individuals." (PMID 40388724, 2025). "Studies have shown that the deubiquitinating enzyme USP16 induces gouty arthritis through Drp1-dependent mitochondrial fission and NLRP3 inflammasome activation, with the mechanism being that USP16 mediates Drp1 deubiquitination and stabilization through direct interaction with Drp1." (PMID 41311848, 2025). "Experimental systems involving NLRP3 inflammasome activation in mouse bone marrow macrophages, along with in vivo mouse models, have been utilized to study the effects of Euodiae fructus (ER), a traditional Chinese medicine, on UA and gout." (PMID 39968300, 2025). "Consistent with our findings, RES improved gouty arthritis, which might inhibit NLRP3 inflammasomes in rats." (PMID 41300457, 2025).
gout (continued). "ATG7 may induce excessive autophagy and activate NLRP3 to release inflammatory cytokines during gout recurrence." (PMID 41221017, 2025). "Previous studies clarified that pharmacological inhibition of NLRP3 inflammasome assembly and activation may also be a promising approach for gouty arthritis treatment." (PMID 40444241, 2025). "Unlike allopurinol, which solely targets XOD, SPP’s concurrent elevation of butyrate, a known NLRP3 inhibitor, may synergistically disrupt the inflammatory cascade driving gout progression." (PMID 40362905, 2025). "Dapansutrile (OLT1177) is defined by its novel, specific NLRP3 inflammasome inhibition, demonstrating consistent mechanisms and broad therapeutic applicability across inflammatory diseases, including gouty arthritis, neurological disorders, and cardiovascular diseases." (PMID 41415576, 2025). "However, most NOD-like receptor family pyrin domain-containing 3 (NLRP3) inhibitors remain in early-stage clinical trials, and their long-term safety and efficacy in gout patients are yet to be fully established." (PMID 40430581, 2025). "A ‘younger’ gut microbiota could suppress the activation of NLRP3, caspase-1, and IL-1β, thereby reducing the inflammatory response in gout." (PMID 39907694, 2025). "Moreover, by inhibiting the NLRP3 inflammasome, oridonin showed protective effects in peritonitis, type-2 DM, and gout." (PMID 38421496, 2024). "Targeting NLRP3 inflammasome, a sensor of metabolic stress, may be a key strategy for the prevention and treatment of gout." (PMID 38708084, 2024). "To ascertain the clinical relevance of NCOA6 as a critical regulator of the NLRP3 inflammasome, we profiled global gene expression in synovial fluid macrophages freshly isolated from gouty arthritis patients (n = 4) in comparison with peripheral blood monocytes from healthy donors (n = 4)." (PMID 38195836, 2024). "Finally, with bioinformatics, in vitro, and in vivo data on the direct role of NCOA6 in the innate immune response and diseases, we suggest NCOA6 as a new therapeutic target for NLRP3-dependent diseases, including gouty arthritis and acute tubular necrosis." (PMID 38195836, 2024). "Furthermore, HECTD3 inhibits monosodium urate crystals (MSU)-induced gouty arthritis, a NLRP3-related disease." (PMID 38267403, 2024). "Additionally, NLRP3 inhibitors have the potential to be effective in treating other inflammatory and autoimmune disorders such as gout, Alzheimer’s disease, and certain cancers, which makes the development of NLRP3 inhibitors a promising area of research." (PMID 38892264, 2024). "The pathophysiology of a variety of inflammatory diseases has a strong connection with the activation of inflammatory proteins, for example, the activation of NLRP3 inflammasome in the case of gout, a severe arthritic disease based on by the accumulation of uric acid crystals in joints." (PMID 38248332, 2024). "However, excessive activation of NLRP3 activation also promoted the development of a number of inflammatory disorders, including type 2 diabetes, inflammatory bowel disease, and gouty arthritis." (PMID 39301021, 2024). "Importantly, ER exerts potent anti-HUA and anti-gout effects by inhibiting UA production, promoting UA excretion, and improving inflammation, at least in part, through the inhibition of NLRP3 inflammasome activation." (PMID 38708084, 2024). "Research has demonstrated the activation of the NLRP3 inflammasome across different autoinflammatory and autoimmune conditions, including gout, rheumatoid arthritis, systemic lupus erythematosus, and more, indicating its crucial involvement in the onset and advancement of inflammatory disorders." (PMID 39245800, 2024). "Topical application of NLRP3 inflammasome inhibitors and IL-1 receptor antagonists may be a new modality in the current treatment of gout combined with DED." (PMID 38376774, 2024).